LINC00352 (long independently transcribed non-coding RNA 352)
Gene: Long non-coding RNA gene on chromosome 13 (23,498,796 to 23,502,874, forward strand). Ensembl gene ENSG00000227893.
Gene Ontology:
Biological process: SRP-dependent cotranslational protein targeting to membrane, signal sequence recognition
Cellular component: signal recognition particle, endoplasmic reticulum targeting